TRIB3 (tribbles pseudokinase 3)
Diseases named in the same sentence as TRIB3 in open-access papers (continued):
Sharing a sentence is not in itself a finding about the gene and the disease.
glioblastoma (8 papers, 2020 to 2025). The most malignant astrocytic tumor (WHO grade IV). "As previously found in other cancer types, the molecular mechanism of action of ABTL0812 in glioblastoma involves the inhibition of Akt/mTORC1 axis by overexpression of TRIB3, and the activation of ER stress and UPR." (PMID 36408162, 2022). "As previously shown in other cancer types, we demonstrated that the molecular mechanism of action of ABTL0812 in glioblastoma involves the inhibition of Akt/mTORC1 axis by overexpression of TRIB3, and the activation of endoplasmic reticulum (ER) stress/unfolded protein response (UPR)." (PMID 36408162, 2022). "However, the underlying regulation and function of TRIB3 in glioblastoma (GBM) is still largely unknown." (PMID 33203798, 2020). "When interrogating the mechanism of action of ABTL0812 in glioblastoma models, we demonstrated that ABTL0812 induces TRIB3 and consequently inhibits Akt/mTORC1 axis, as indicated by a reduction of p-Akt and of the mTORC1 substrate p-p70S6K." (PMID 36408162, 2022). "Similarly, TRIB3, upregulated in both TMZ and TMZ + TO‐treated glioblastoma cells, plays an important role in proliferation and osteogenic differentiation but also has been shown to be involved in endoplasmatic reticulum stress‐dependent apoptotic cell death." (PMID 39680504, 2025). "The mRNA expression of TRIB3 in glioblastoma clinical samples was higher than that in normal brain tissue." (PMID 39118481, 2024).
liver cancer (8 papers, 2020 to 2025). An epithelial or non-epithelial malignant neoplasm that arises from the liver. "Studies have reported that TRIB3 can regulate cell metabolism via PI3K/AKT/mTOR circuit for liver cancer, oral and nasopharyngeal carcinoma." (PMID 39869954, 2025). "In contrast, TRIB3 can repress certain TFs, as seen in liver cancer cells treated with bortezomib, where it binds to ATF4 on chromatin." (PMID 41287970, 2025). "Thus, TRIB3 is a novel factor contributing to bortezomib resistance of liver cancer cells." (PMID 34066165, 2021). "We found that the pseudokinase TRIB3, an endogenous regulator of ATF4 and a gene highly expressed in liver cancer, resides predominantly at the same chromatin sites as ATF4 and constrains ATF4 activity." (PMID 34066165, 2021). "However, regardless of whether treated with sorafenib or not, overexpression of TRIB3 did not affect the migration of liver cancer cells, nor did it alter the expression of E‐cadherin and vimentin." (PMID 39932456, 2025).
liver fibrosis (8 papers, 2016 to 2025). "Furthermore, TRIB3 is a stress protein upregulated in response to multiple stressors; its elevated expression positively correlates with the development of human hepatic fibrosis associated with suppressed autophagy." (PMID 36834506, 2023). "Studies have shown that STK4 and TRIB3 further participate in the occurrence and development of liver fibrosis by regulating the level of autophagy." (PMID 40368138, 2025). "Disrupting the TRIB3‐SQSTM1 interaction reduced liver fibrosis by restoring autophagy and inhibiting exosome‐mediated HSC activation." (PMID 33506641, 2021). "Several secreted or intracellular factors related to cell regulation (“signaling pathway”) were also upregulated, some of them (Trib3, CTGF/CCN2, Egr1, Stat3...) having been linked to inflammation, tissue repair, liver fibrosis and TGFβ signaling." (PMID 26446156, 2016). "Abnormal expression of TRIB3 protein causes liver fibrosis, suggesting that the normal expression of TRIB3 protein plays an important role in various physiological and pathological processes in human tissues and organs." (PMID 32874132, 2020). "Autophagy impairment mediated by TRIB3 and the selective autophagy receptor SQSTM1 in human liver fibrosis promoted the secretion of harmful exosomes, which induced the migration, proliferation and activation of HSCs." (PMID 33506641, 2021). "For example, stress-induced tribbles pseudokinase 3 (TRIB3) interacted with sequestosome 1 (SQSTM1) to enhance the secretion of INHBA/Activin A-rich exosomes from hepatocytes, thereby activating hepatic stellate cells (HSCs) and promoting liver fibrosis." (PMID 40771315, 2025).
lymphoma (8 papers, 2020 to 2025). A malignant (clonal) proliferation of B- lymphocytes or T- lymphocytes which involves the lymph nodes, bone marrow and/or extranodal sites. "We sequenced the coding region of TRIB3 in 89 human lymphoma samples to identify nonsynonymous variants." (PMID 33298911, 2020). "Histological analysis revealed reduced tumor foci in the spleens and LNs of tamoxifen-treated MycEμCreERT2Trib3F/+ mice compared to lymphoma-matched vehicle recipients, which was caused by the tamoxifen-induced loss of TRIB3 in lymphoma tissues." (PMID 33298911, 2020). "Thus, the lymphoma-promoting roles of TRIB3 are associated with increased MYC stabilization in lymphoma cells." (PMID 33298911, 2020). "Hence, we presumed that the decreased protein expression of TRIB2 is caused by TRIB3 knockout-reduced TRIB2 transcription through suppressing the activity of Wnt/β-catenin in lymphoma cells." (PMID 33298911, 2020). "Disrupting this TRIB3‐MYC interaction reduced tumor burden in a mouse lymphoma model and patient‐derived xenografts." (PMID 41287970, 2025). "The mechanism of TRIB3 has been investigated; previous studies have shown that TRIB3 promotes MYC-associated lymphoma development through suppression of UBE3B-mediated MYC degradation." (PMID 35726370, 2022). "We examined the expression and roles of TRIB3 in primary lymphoma cells from patients and patient-derived xenograft (PDX) mice." (PMID 33298911, 2020). "Taken together, these data indicated that K427 of MYC is critical for UBE3B-catalyzed MYC ubiquitination and the functions of TRIB3 in promoting lymphoma cell growth are dependent on T58 phosphorylation of MYC." (PMID 33298911, 2020). "Ube3b overexpression reduced the enlarged spleens and LNs and reduced the number of Ki-67-positive cells in the spleens of lymphoma mice, which was reversed by TRIB3 overexpression." (PMID 33298911, 2020). "Our study highlights a key mechanism for controlling MYC expression and a potential therapeutic option for treating lymphomas with high TRIB3-MYC expression." (PMID 33298911, 2020). "Using transgenic mice with Trib3 deletion in different cell lineages, we found that TRIB3 participated in MYC-driven lymphoma tumorigenesis and pathogenesis." (PMID 33298911, 2020). "In this study, we found that lymphoma cells with high TRIB3 and MYC expression were more sensitive to PCM4 than those with low TRIB3 or MYC expression and that PCM4 increased the sensitivity of lymphoma cells to DOX due to decreased MYC expression." (PMID 33298911, 2020). "TRIB3 knockout suppresses the cell proliferation and self-renewal ability of MYC-associated lymphoma by reducing MYC protein stability and abundance in these cells." (PMID 33298911, 2020). "Here, we report that high expression of tribbles homologue 3 (TRIB3) positively correlates with elevated MYC expression in lymphoma specimens; TRIB3 deletion attenuates the initiation and progression of MYC-driven lymphoma by reducing MYC expression." (PMID 33298911, 2020). "In this study, we observed that TRIB3 expression was elevated in more than 50% of human lymphoma cases." (PMID 33298911, 2020). "TRIB3 interacted with MYC to suppress E3 ubiquitin ligase UBE3B-mediated MYC degradation, which induced the enhanced expression of MYC, causing the proliferation of lymphoma cells." (PMID 35668944, 2022). "In addition, a recent study demonstrated that suppression of the E3 ubiquitin ligase UBE3B-mediated MYC ubiquitination and degradation caused by the integration of TRIB3 with MYC is associated with high proliferation and self-renewal of lymphoma cells." (PMID 33652974, 2021). "Moreover, B lymphocyte-specific ablation of Trib3 resulted in the extended survival of mice with lymphoma." (PMID 33298911, 2020). "Mechanistically, TRIB3 interacts with MYC to suppress E3 ubiquitin ligase UBE3B-mediated MYC ubiquitination and degradation, which enhances MYC transcriptional activity, causing high proliferation and self-renewal of lymphoma cells." (PMID 33298911, 2020).
lymphoma (continued). "We found that TRIB3 interacts with MYC to suppress E3 ubiquitin ligase UBE3B-mediated MYC ubiquitination and degradation, which causes high proliferation and self-renewal of lymphoma cells." (PMID 33298911, 2020). "We evaluated the effects of UBE3B and TRIB3 on lymphoma development in MycEμ mice." (PMID 33298911, 2020). "In this work, we hypothesize that TRIB3 contributes to lymphoma pathogenesis by promoting MYC-deregulated lymphomagenesis." (PMID 33298911, 2020). "Notably, TRIB3 knockdown reduced MYC expression in most lymphoma lines and in some leukemia lines." (PMID 33298911, 2020). "Thus, Trib3 depletion-reduced TRIB2 expression in lymphoma cells may contribute to lymphoma pathogenesis in MycEμCreCD19Trib3F/+ mice." (PMID 33298911, 2020). "Thus, high MYC expression may be mainly caused by a decreased interaction of UBE3B and MYC, which is induced by elevated TRIB3 expression in lymphoma cells." (PMID 33298911, 2020). "Moreover, restored expression of full-length TRIB3 or the KDC domain of TRIB3 reversed the repressed proliferation of lymphoma cells induced by TRIB3 deletion, indicating that the KDC domain of TRIB3 interacts with MYC, which stabilizes MYC and enhances lymphoma cell proliferation." (PMID 33298911, 2020). "Interestingly, the TRIB3 Q84R mutant was shown to be more stable than wild-type (WT) TRIB3, which may result in high TRIB3 expression in human lymphomas." (PMID 33298911, 2020). "Several mechanisms may account for TRIB3 ablation-induced lymphoma inhibition." (PMID 33298911, 2020). "To determine whether TRIB3 was required for not only lymphoma initiation but also the malignancy of established lymphomas, we crossed Trib3F/F mice with CreERT2 mice to generate CreERT2Trib3F/F mice, enabling temporally controlled Cre activation by tamoxifen treatment." (PMID 33298911, 2020). "Thus, TRIB3 promotes lymphoma by supporting lymphoma cell self-renewal ability and proliferation." (PMID 33298911, 2020). "Knocking out TRIB3 in primary human DLBCL (T69), BL (T4 and T5), and PTCL (T144) cells freshly isolated from patient tumors or lymphoma cell lines reduced the colony-formation units (CFUs) and proliferation." (PMID 33298911, 2020). "In summary, our study indicates that TRIB3 is a reasonable molecular target for the treatment of high MYC-expressing lymphoma and that interruption of the MYC-TRIB3 and MYC-MAX interactions has therapeutic potential for this lymphoma." (PMID 33298911, 2020). "Here, the authors show that a member of the pseudokinase family, tribbles homologue 3 (TRIB3), interacts with c-MYC to suppress c-MYC ubiquitination and degradation, leading to increased proliferation and self-renewal of lymphoma cells." (PMID 33298911, 2020). "The pathophysiological relevance of UBE3B, TRIB3 and MYC is further demonstrated in human lymphoma." (PMID 33298911, 2020). "Through RNA sequencing (RNA-seq), we analyzed the gene expression profiles of lymphoma cells with or without Trib3 deletion." (PMID 33298911, 2020). "Further, MYC, TRIB3, and MAX formed the heterotrimer in lymphoma cells." (PMID 33298911, 2020). "Indeed, TRIB3 interacted with MYC in Raji cells, which was supported by the colocalization of TRIB3/MYC in human lymphoma cells." (PMID 33298911, 2020). "Trib3 deletion in B lymphocytes, but not in myeloid cells or T lymphocytes, inhibited lymphoma development." (PMID 33298911, 2020). "In comparison with the benign LN tissues, most lymphoma specimens showed high expression of TRIB3 but not UBE3B." (PMID 33298911, 2020). "TRIB3 deletion did not induce a sub-G1 fraction of the cellular DNA content, nor did it increase CD11b positive cells ratio in FACS analysis, suggesting that TRIB3 depletion does not induce cell death or differentiation in lymphoma cells." (PMID 33298911, 2020).
colon carcinoma (7 papers, 2016 to 2025). "Plate clone and transwell assays demonstrated that TRIB3 promoted the proliferation, invasion, and metastasis of colon cancer cells." (PMID 39665272, 2025). "A very recent report showed that down-regulating TRIB3 in different colon carcinoma cell lines, such as SW480, HCT116, CaCO2, SW48 and SKCO1, led to a mesenchymal-epithelial transition (MET) phenotype." (PMID 34198908, 2021). "On the other hand, TRIB3 was associated, together with other immune-related genes such as CHGA, LGALS4, LEP, NOX4, IL17A, HSPD1, and CASP7, with colon cancer prognosis." (PMID 34198908, 2021). "TRIB3 was highly expressed in colon tumor tissues, moderately in lung and esophageal, very limited in stomach, but not increased in liver or kidney cancers." (PMID 34198908, 2021). "Alongside the analysis of the tumor-infiltrating immune cells in colon cancer, a novel predictive tool for colon cancer prognosis, which included TRIB3 levels, was established." (PMID 34198908, 2021). "Activated β-catenin not only increases TRIB3 transcription but also supports TRIB3 stability, indicating a positive feedback loop between WNT/β-catenin signaling and TRIB3 expression in the induction and support of colon cancer stemness." (PMID 33334065, 2020). "TCGA indicated elevated expression of TRIB3 in colon cancer tissues." (PMID 39665272, 2025). "Interestingly, the authors discovered that TRIB3 was overexpressed in all the colon cancer tissue pairs analyzed." (PMID 34198908, 2021). "Intriguingly, it was found that two TRIB3 spliced isoforms were overexpressed in colon tumors." (PMID 34198908, 2021). "In addition, TRIB3 also shows a significant correlation with worse OS in colon cancer." (PMID 33038770, 2020). "Although not shown, the authors described a significant higher TRIB3 gene expression in colon-carcinoma compared to the corresponding normal tissues." (PMID 34198908, 2021). "Though initially stated as “data not shown”, the very first input on TRIB3 gene overexpression in colon tumor samples, when compared to matched normal colon samples, was published in 2003, much earlier than the other two Tribbles family members." (PMID 34198908, 2021). "Our recent study indicated that TRIB3 depletion decreased β-catenin/TCF transcriptional activity by reducing the recruitment of TCF and β-catenin to the promoter region of genes regulated by Wnt in colon cancer cells." (PMID 33298911, 2020).
renal cell carcinoma (7 papers, 2020 to 2025). "Among these, EGFR and CD4 exhibited a protective role in renal cell carcinoma, whereas TRIB3 and ZAP70 were identified as risk factors (P - value <0.05)." (PMID 40104395, 2025). "TRIB3 has been associated with HIF-1α in renal cell carcinoma patients with HIF-1α binding to multiple regions in the TRIB3 promoter resulting in upregulation of TRIB3 expression." (PMID 38896446, 2024). "TRIB3 can promote cell proliferation in Renal Cell Carcinoma Cells by MAPK Signaling Pathway." (PMID 37189176, 2023). "In the same way, in renal cell carcinoma, gastric cancer, oral tongue squamous cell carcinoma, and non-small-cell lung carcinoma, the upregulated TRIB3 expression correlates with tumor stage, lymph node metastasis, disease recurrence, and thus with unfavorable prognosis." (PMID 33920424, 2021). "Finally, we illustrated that TRIB3 might be a protumor factor responsible for the elevated proliferation and invasion capacities of renal cell carcinoma (RCC) cells." (PMID 38006403, 2023). "In renal cell carcinoma (RCC), researchers have found that high expression of TRIB3, which is induced by HIF-1α, enhanced cell proliferation, migration and invasion abilities by regulating the MAPK pathway." (PMID 32874132, 2020).
ovarian carcinoma (6 papers, 2020 to 2025). A malignant neoplasm originating from the surface ovarian epithelium. "Studies confirmed that inhibition of the expression of TRIB3 in ovarian cancer cells causes cell cycle arrest in the G0/G1 phase in ovarian cancer cells." (PMID 33841505, 2021). "In summary, this study showed that TRIB3 was significantly over-expressed in ovarian cancer tissues and was associated with poor prognosis of ovarian cancer." (PMID 32874132, 2020). "Analysis of TRIB3 in the TISIDB database and cBioPortal website showed that ovarian cancer patients with high levels of mutation in TRIB3 had poor prognosis, and that the expression of TRIB3 was related to immunomodulation." (PMID 32874132, 2020). "However, the Kaplan-Meier survival analysis showed that the high expression level of TRIB3 in ovarian cancer cells was significantly associated with short survival rates and poor prognosis, as supported by the analysis in the KM-plot website." (PMID 32874132, 2020). "It is hypothesized that TRIB3 may be associated with the malignant behavior of ovarian cancer." (PMID 32874132, 2020). "Survival analysis showed that the survival time of ovarian cancer patients with the TRIB3 mutation was significantly shorter as compared to that of patients without the mutation, indicating that the TRIB3 mutation can predict the survival and prognosis of patients with ovarian cancer." (PMID 32874132, 2020). "Though CAAs can modulate ovarian cancer metastasis, studies also reported that ovarian cancer can induce CAA formation via activating the TGF-β1/SMAD3/TRIB3 pathway in reverse, which suppresses the phosphorylation of CEBPβ." (PMID 40709184, 2025). "A total of 1,680 ovarian cancer cases were analyzed for genetic changes in TRIB3, in the cBioPortal website." (PMID 32874132, 2020). "Following down-regulation of TRIB3 by siRNA, multiple aspects of ovarian cancer cells were detected by the MTT assay, flow cytometry, scratch test and Transwell." (PMID 32874132, 2020). "Down-regulation of TRIB3 expression significantly inhibited the proliferation, invasion, and migration capabilities of ovarian cancer cells, and induced apoptosis and cell cycle arrest." (PMID 32874132, 2020). "The degree of TRIB3 high positive expression in the ovarian cancer group (60.6%) was significantly higher than that in the borderline group (25%), benign group (7.1%), and normal ovarian tissue groups (0%)." (PMID 32874132, 2020). "And we found that there was a reduction in the phosphorylation of MEK proteins and ERK proteins in ovarian cancer cell lines following inhibition of TRIB3 expression." (PMID 32874132, 2020). "The positive expression level of TRIB3 was higher (75.7%) in the ovarian cancer group as compared to the level observed in the borderline group (50%) (P > 0.05)." (PMID 32874132, 2020). "Survival analysis revealed significantly short survival times in ovarian cancer patients with altered TRIB3 gene (P = 4.796 × 10− 03)." (PMID 32874132, 2020). "According to the cBioPortal database, it was found that the genetic changes in TRIB3 was less than 10% as compared to the genetic changes of other genes involved in ovarian cancers." (PMID 32874132, 2020). "Univariate Cox regression analysis suggested that TRIB3 expression, the FIGO stage of the cancer, and lymph node metastasis were risk factors for the prognosis of ovarian cancer." (PMID 32874132, 2020). "In order to further explore the effect of TRIB3 down-regulation on the invasion and migration of ovarian cancer cells, the Transwell was used to measure the changes in cell invasion of these two cell lines." (PMID 32874132, 2020). "In patients with advanced ovarian cancer, the extent of TRIB3 expression was found to be 58.6%, that was higher than that observed in patients with early stage of the disease (50%) (P > 0.05)." (PMID 32874132, 2020). "The TRIB3 was highly expressed and promoting the malignant behavior of ovarian cancer cells by activating the MEK-ERK signaling pathway." (PMID 32874132, 2020).